SOD2 (superoxide dismutase 2)
Diseases named in the same sentence as SOD2 in open-access papers (continued):
Sharing a sentence is not in itself a finding about the gene and the disease.
asthma (18 papers, 2013 to 2026). "After adjusting for confounding factors such as gender and age, these five genes (CEBPE, HDC, IRAK3, PRR4, and SOD2) were still independent risk factors for asthma." (PMID 41602038, 2026). "By conducting bioinformatics analysis, we identified five genes (CEBPE, HDC, IRAK3, PRR4, and SOD2) associated with asthma." (PMID 41602038, 2026). "Results of this case-control study suggests that phthalate exposure and SOD2 rs5746136 variants were significantly associated with asthma." (PMID 28208751, 2017). "The SOD2 (rs5746136) was significantly associated with a higher odds of asthma for the TT genotype with adjusted OR (95% CI) of 2.78 (1.54–5.02) (Bonferroni p = 0.009) compared with the CC genotype." (PMID 28208751, 2017). "Our findings suggest a possible role of the SOD2 gene modifying the association of phthalates with asthma." (PMID 28208751, 2017). "Genetic variants of SOD2, which can reflect oxidative stress metabolism, might modify the association of phthalate exposure with asthma." (PMID 41602038, 2026). "It has also been proposed that genetic variants of SOD2 might modify the association between urinary concentrations of phthalates and the risk of asthma, which was increased in patients with the TT SOD2 variant (related to higher oxidative stress levels)." (PMID 32069886, 2020). "Since only SOD2 TT genotype was significantly associated with asthma (adjusted OR (95% CI): 2.78 (1.54–5.02)), we estimated whether SOD2 variants modify the association of MEHHP levels and asthma." (PMID 28208751, 2017). "Our results support the involvement of genetic polymorphisms of SOD2 in asthma." (PMID 28208751, 2017). "Genetic variants of SOD2, considered to be reflect oxidative stress metabolisms, might modify the association of phthalate exposure with asthma." (PMID 28208751, 2017). "In addition, genetic variants to SOD2 in interaction with MEHHP seems to constitute a higher risk of asthma." (PMID 28208751, 2017). "Supporting a role for Nrf2 in inflammatory allergic responses against airborne particles, polymorphisms in NRF2 and ARE-responsive antioxidant genes (GSTP1, SOD2) were associated with a trend toward increased risk of hospitalization during periods of high outdoor PM in an asthma/COPD cohort." (PMID 23766849, 2013). "Additionally, epigenetic modifications to the fetal genome during in utero PM exposure can further increase the risk of asthma, such as the antioxidant superoxide dismutase 2 (SOD2) promoter DNA methylation, and TMEM184A which is involved in the inflammatory response." (PMID 37008013, 2023). "In addition, genetic variants of the SOD2 gene might modify the association of phthalate exposure with asthma." (PMID 28208751, 2017). "The H2O2-poly(I:C) co-stimulation dose-dependently reduced gene and protein levels of SOD2 and partially SOD1, thus mimicking clinical findings of antioxidant deficiency at asthma exacerbation." (PMID 31849956, 2019). "A case-control study demonstrated that genetic variants of antioxidant defense genes, SOD2, GST, and EPHX1, were associated with increased susceptibility to diisocyanate-induced asthma." (PMID 28208751, 2017). "A significant different effect of genotypes was found among asthma cases and controls for GSTP1 (rs1695) and SOD2 (rs5746136) polymorphisms; however, only the effect of SOD2 survived the penalty for multiple testing." (PMID 28208751, 2017). "To determine the role of these key genes in the occurrence of asthma caused by environmental pollution, we provided strong evidence that the expression of genes of interest (CEBPE, HDC, IRAK3, PRR4, and SOD2) increased significantly in 160 participants with asthma." (PMID 41602038, 2026). "Finally, for the path where PM2.5 affects asthma through SOD2, the indirect effect was 0.01 [95% CI (0.028, 0.074), p = 0.419], with an SE of 0.012 and a z/t value of 0.808." (PMID 41602038, 2026). "The reduction of SOD2 mRNA expression was also observed in our study from mild to severe asthma." (PMID 32117613, 2020).
asthma (continued). "Then we tested the interaction of the phthalate residuals with SOD2 gene on asthma." (PMID 28208751, 2017). "Finally, five genes (CEBPE, HDC, IRAK3, PRR4, and SOD2) were identified as overlapping features across all three algorithms, as illustrated in the Venn diagram, and were thus considered robust candidate biomarkers for asthma." (PMID 41602038, 2026). "In addition, these five gene have also been associated with the occurrence of asthma in different exposure settings and oxidative stress-related genetic variants of CAT, SOD2 and MPO have been reported to modify the association of urine phthalate metabolites levels and pulmonary function." (PMID 28208751, 2017). "In this study, a mediation effect analysis was conducted to elucidate the potential mediating mechanisms between PM2.5 and the onset of asthma, involving several potential mediators, including CEBPE, HDC, IRAK3, PRR4, and SOD2." (PMID 41602038, 2026). "This study provided evidence that CEBPE, HDC, IRAK3, PRR4, and SOD2 mediate the connection between PM2.5 and the onset of asthma." (PMID 41602038, 2026). "In our study, DNP-HSA stimulation decreased the gene expression of SOD2 and CAT in RBL-2H3 cells, consistent with similar findings reported in patients with asthma." (PMID 38790633, 2024). "Prenatal PM10 exposure is likely to induce superoxide dismutase 2 (SOD2) protomer methylation in cord blood cells, which is related to phthalate and diisocyanate-induced asthma." (PMID 35453508, 2022). "Prenatal PM10 exposure induced superoxide dismutase 2 (SOD2) protomer methylation in cord blood cells, which is related to phthalate and diisocyanate-induced asthma." (PMID 32117969, 2020). "Further, since SOD2 was associated with asthma, but GSTP1 was not, and MEHHP urine levels differ with genotypes of SOD2, we focused on the interplay of SOD2 and MEHHP with asthma." (PMID 28208751, 2017). "The results revealed that five genes of interest (CEBPE, HDC, IRAK3, PRR4, and SOD2) showed a strong mediating effect between PM2.5 and the onset of asthma, suggesting that PM2.5 may alter the expression of these genes, thereby causing the onset of asthma." (PMID 41602038, 2026). "Before we can estimate whether there is an interaction between SOD2 and MEHHP resulting in a higher odds of having asthma, we need to estimate the part of MEHHP that is not explained by SOD2 (the residuals)." (PMID 28208751, 2017).
diabetic retinopathy (18 papers, 2007 to 2025). "In the pathogenesis of diabetic retinopathy, Sod2, the MnSOD encoding gene, is epigenetically modified with increased H4K20me3, acetyl H3K9, and p65 subunit of NF-kB (p65) at its promoter/enhancer." (PMID 24286082, 2013). "Overexpression of Sod2, which protects the retina from increased accumulation of mitochondrial superoxide and the development of diabetic retinopathy, also prevents reductions in MRPP1 and its interactions with LncCytB and restores LncCytB expression." (PMID 39200102, 2024). "SUV420h2 and LSD1 both repress Sod2 transcription to reduce the ability of Sod2 to remove ROS and thus contribute to oxidative stress during the development of diabetic retinopathy." (PMID 35340204, 2022). "Overexpression of Sod2 in mice prevents diabetes-induced mitochondrial damage and protects them from developing diabetic retinopathy, strengthening the role of mitochondria in diabetic retinopathy." (PMID 32961662, 2020). "A study was performed in the streptozotocin-induced diabetic rat model to evaluate epigenetic regulation of manganese superoxide dismutase (Sod2) and its potential role in the development of diabetic retinopathy." (PMID 24179439, 2013). "Additionally, methylation of histone 4 lysine 20 at SOD2 (superoxide dismutase-2) downregulates the antioxidant, exacerbating diabetic retinopathy and reinforcing metabolic memory of retinal cells." (PMID 38323108, 2024). "However, in Sod2-overexpressing diabetic mice (Sod-D), the mice that were protected from downregulation of LncCytB and the development of diabetic retinopathy, relative MRPP1 gene transcripts were similar to those in the WT-N group." (PMID 39200102, 2024). "In the pathogenesis of diabetic retinopathy, increased oxidative stress is considered to play a major role, and our studies have shown that the control of oxidative stress prevents epigenetic changes in retinal Sod2." (PMID 24286082, 2013). "In human diabetic retinopathy, the histone hypomethylation of H3K4 is accompanied by a down-regulation of gene expression for the antioxidant enzyme superoxide dismutase 2 (SOD2)." (PMID 31212911, 2019). "Similar to our previous findings in a diabetic retinopathy model, LG treatment did not result in an increase of HO-1, SOD-2 or GCLC expression, indicating that the antioxidant effect of LG is likely to be due to its radical scavenging properties." (PMID 34393798, 2021).
cervical carcinoma (17 papers, 2014 to 2025). A carcinoma arising from either the exocervical squamous epithelium or the endocervical glandular epithelium. "The presence of SOD2 has also been associated with pelvic lymph node metastasis in patients with early stage cervical carcinoma." (PMID 34062984, 2021). "A microarray approach found SOD2 to be differentially expressed in a gene expression signature and associated with pelvic lymph node metastasis in cervical cancer." (PMID 34062984, 2021). "The first is whether SOD2 expression is associated with the prognosis for earlier invasive cervical cancer as it is in more advanced cases." (PMID 34062984, 2021). "However, this study showed a clear statistical association between SOD2 expression and the prognosis of cervical cancer, which strongly suggests the existence of a relevant biological event." (PMID 34062984, 2021). "The aim of this study was to determine whether SOD2 protein expression is associated with the prognosis of stage IIIB cervical carcinoma." (PMID 34062984, 2021). "This study aims to determine whether SOD2 protein expression is associated with the prognosis of stage IIIB cervical carcinoma." (PMID 34062984, 2021). "Additionally, the SOD2 gene integrates a group of 11 genes identified as a signature of 33-fold increased risk for predicting pelvic lymph node metastasis in cervical carcinoma." (PMID 29774090, 2018). "In cervical cancer, genetic studies have explored the correlation between HPV integration patterns and SOD2 gene polymorphisms." (PMID 40244057, 2025). "High superoxide dismutase 2 (SOD2) expression is associated with a poor prognosis at many cancer sites, the presence of metastases, and more advanced cervical cancer." (PMID 34062984, 2021). "The univariate analysis of data from our study showed that high SOD2 expression was associated with reduced disease-free survival (DFS) and overall survival (OS) in patients with cervical cancer." (PMID 34062984, 2021). "The results indicated that Fra-1 up-regulated the expression of SIRT3, which led to changes in IDH2 and SOD2 expression as downstream molecules, and finally reduced the ROS content in cervical cancer cells." (PMID 33102485, 2020). "Several studies have shown that superoxide dismutase 2 (SOD2 or manganese superoxide dismutase) protein expression is up-regulated in colorectal, lung, gastric/esophageal, and cervical cancer cells when compared to normal tissues." (PMID 25745358, 2015). "Activation of LPA3 with its highly selective agonist, OMPT, showed potent induction of mitochondrial antioxidants, glutathione peroxidase 1 (Gpx1), and superoxide dismutase type 1 and type 2 (SOD1 and SOD2) protein expression in human cervical cancer HeLa cells." (PMID 35204233, 2022). "Infection by HPV 16 and 18 are the strongest risk factors for cervical cancer development, but the expression of SOD2 seems to be a risk factor independent of the role of the HPV infection." (PMID 34062984, 2021). "Therefore, we examined the effect of Fra-1 overexpression on SIRT3, IDH2, and SOD2 expression in cervical cancer cells." (PMID 33102485, 2020). "Moreover, although the main cause of cervical cancer development is persistent high-risk HPV infections, there is evidence that SOD2 expression may play a role in the carcinogenesis of cervical epithelium independently of the type of HPV." (PMID 34062984, 2021). "We found that Fra-1 overexpression restored mitochondrial function in cervical cancer cells via the SIRT3 signaling pathway, and Fra-1 increased the expression of IDH2 and SOD2." (PMID 33102485, 2020). "Conclusion: high SOD2 expression is a strong prognostic factor for stage IIIB squamous cell carcinoma of the cervix and could be used as a prognostic marker in women with cervical carcinoma." (PMID 34062984, 2021).
cervical carcinoma (continued). "In conclusion, our results showed that the expression of SOD2 was increased in CIN3 and SCC, and more increased in cervical ADC than in SCC, and this pattern of SOD2 expression was statistically independent of the presence of HPV 16 and/or 18, the most prevalent types in the cervical cancer." (PMID 29774090, 2018).
colitis (17 papers, 2011 to 2025). Inflammation of the colon. "Colitis reduced colonic Sod2, Gpx1, and Prdx1 (peroxiredoxin) by 37%, 29%, and 58%, respectively, compared to the non-colitic control." (PMID 31212794, 2019). "The expression of “SOD2” was significantly (P < 0.000) downregulated in colitis-induced mice at the level of –100.00-fold relative to PBS control group." (PMID 25061603, 2014). "Studies report that in mice with colitis SOD2 is downregulated." (PMID 40002416, 2025). "Our study showed that both SOD1 and SOD2 are downregulated in experimental colitis." (PMID 38668322, 2024). "However, when mice with colitis fed an SD were subjected to voluntary exercise, a significant increase in the mRNA expression of SOD2 was observed compared to that measured in the sedentary SD mice (p < 0.05)." (PMID 33557311, 2021). "Interestingly, the mRNA level of Nrf2 in the colon was not affected by the T cell transfer, although the mRNA expression of SOD2 and Gpx1 was lowered by colitis but maintained by aronia feeding." (PMID 31212794, 2019). "The expression of SOD2 was significantly downregulated in colitis-induced mice by −100.00-fold relative to control group, and the downregulation was considerably reduced to −37.04-fold in colitis Lf1 treatment group." (PMID 25061603, 2014). "However, when the colitis-induced mice group was fed with Lf1, the downregulation was considerably reduced to −37.037-fold indicating that there was actually a substantial increase (approximately 63%) in the expression of “SOD2” gene under these conditions." (PMID 25061603, 2014). "Thus, we assessed the main antioxidant enzymes (SOD1, SOD2, CAT, GPx) in a TNBS-induced colitis model in animals previously treated with BC." (PMID 40002416, 2025). "Also, relief of IBD symptoms was observed along with increased expression of antioxidant enzymes such as SOD2 and TrxR-1, and decreased thioredoxin in L. fermentum Lf1-fed DSS colitis mice." (PMID 39849930, 2024). "In the spleen, Nfe2l2, Gclc, Gsr, Sod2, Gpx1, Gpx2, and Prdx1 were not consistently affected by T cell transfer colitis." (PMID 31212794, 2019). "The mucosal expression of mRNA for TNF-α, IL-1β, iNOS, COX-2, SOD-1, SOD-2, GPx mRNAs, and the hypoxia inducible factor (HIF)-1α protein expression were upregulated in colonic mucosa of treadmill exercising HFD mice with colitis compared with those without exercise." (PMID 31117199, 2019).
schizophrenia (17 papers, 2006 to 2025). A major psychotic disorder characterized by abnormalities in the perception or expression of reality. "The SOD2 rs4880 G allele and higher SOD2 enzyme activity have been linked to impaired attention in adults with schizophrenia." (PMID 34387669, 2022). "In contrast, other studies have reported the SOD2 rs4880 A allele is associated with higher risk of schizophrenia and depression compared with the G allele." (PMID 34387669, 2022). "A large multi-site study with 923 schizophrenia inpatients found that SOD2 rs4880 G-allele carriers showed poorer attention in the schizophrenia group compared with the AA homozygous group." (PMID 34387669, 2022). "An analysis of TRPV1, Sirt3, SOD2, and acetyl-SOD2 in the PBMCs and ADEs of the patients with schizophrenia showed that TRPV1 in the PBMCs exhibited a positive correlation with that in the ADEs." (PMID 40309794, 2025). "In this study, we found a marked downregulation of Sirt3 and upregulation of SOD2 and acetyl-SOD2 in both the PBMCs and ADEs of patients with schizophrenia relative to the controls." (PMID 40309794, 2025). "Our study also found that SOD2 and other oxidative stress markers were positively correlated with the positive symptoms in patients with acute onset schizophrenia." (PMID 40309794, 2025). "No differentially expressed genes were identified in either the PD or the schizophrenia cohorts, and only one gene (superoxide dismutase 2, SOD2) was identified as being differentially expressed between patients and TECs in the PTSD cohort." (PMID 37861850, 2022). "In post‐mortem clinical studies, increases in SOD1 and SOD2 levels were found in frontal cortex of patients with schizophrenia and in prefrontal cortex of depressive subjects." (PMID 32281745, 2020). "In this study, the detection of ADEs revealed that, similar to the findings in PBMCs, the TRPV1 and Sirt3 expressions were significantly downregulated, while the SOD2 and acetyl-SOD2 expressions were significantly increased in patients with schizophrenia compared with those of the HC group." (PMID 40309794, 2025).
chronic kidney disease (15 papers, 2016 to 2026). Impairment of the renal function secondary to chronic kidney damage persisting for three or more months. "In the setting of chronic kidney disease, Nrf2 (−617 C/A) rs6721961, MnSOD (SOD2) rs4880, and GPx1 rs1050450 polymorphisms have been described as predictors of overall survival." (PMID 35326157, 2022). "The SOD2 rs4880 polymorphism is believed to be associated with the susceptibility to various diseases, including cancer, neurodegenerative disorders, chronic kidney disease (CKD), and cardiovascular diseases." (PMID 38983269, 2024). "It is important to note that polymorphic expression of either SOD2 and/or GPX1 influences susceptibility to end-stage renal disease (ESRD) and transitional cell carcinoma (TCC), both associated with BEN progression and complications." (PMID 31382611, 2019). "We assessed the association between polymorphisms in Nrf2, superoxide dismutase (SOD2), glutathione peroxidase (GPX1), and the risk of end-stage renal disease (ESRD)." (PMID 31340563, 2019). "Cluster 2 captured the metabolic decline, with loss of Cystathionine beta‐synthase (CBS), a critical enzyme in sulfur amino acid metabolism and linked to oxidative stress and chronic kidney disease (CKD), and Sirt3, a regulator of mitochondrial ROS through Superoxide dismutase (SOD2)." (PMID 41508419, 2026). "In chronic kidney disease, contrasting results about SOD2 enzyme were reported." (PMID 27630759, 2016). "Human data on SOD2 protein content in chronic kidney disease (CKD) are sparse and mortality data are lacking." (PMID 27630759, 2016). "We prospectively enrolled multicenter patients with end-stage renal disease (ESRD) and those without chronic kidney disease (CKD) of Han Chinese origin, with SOD2 (Val16Ala), GPX1 (Pro197Leu), and PPAR-γ (Pro12Ala, C161T) genotyped." (PMID 26881045, 2016).